IFNG (interferon gamma)
Diseases named in the same sentence as IFNG in open-access papers (continued):
Sharing a sentence is not in itself a finding about the gene and the disease.
COVID-19 (continued). "Notably, in the recent COVID-19 outbreak, a cytokine profile resembling sHLH was found to be associated with COVID-19 disease severity, characterized by increased cytokines such as IFNγ, MCP-1, MIP1-α, and TNFα." (PMID 33823154, 2021). "Moreover, higher levels of IFNγ TNFα, IL-2, and IL-10 have been associated with COVID-19 severity, further supporting a pathogenic role." (PMID 33634100, 2020). "This may be due to increased expression of cytokines, including interleukin (IL)-2, IL-6, IL-7, tumor necrosis factor, granulocyte colony-stimulating factor, interferon-gamma, and free radicals associated with the severity of COVID-19." (PMID 32953353, 2020). "CBD was also shown to reduce interleukin (IL)-2, IL-1α and β, interferon gamma, inducible protein-10, monocyte chemoattractant protein-1, macrophage inflammatory protein-1α, and tumor necrosis factor-α – all of which are associated with the pathology of severe cases of COVID-19." (PMID 36844029, 2023). "The pathway analysis of WB samples from patients with COVID-19 compared with HC showed notable enrichment of genes in multiple pathways associated with “inflammatory response”, “interferon-alpha”, “G2M checkpoint”, “mitotic spindle”, and “interferon-gamma response” as well as “KRAS Signaling Up”." (PMID 35922752, 2022). "However, when stratified according to sex, levels of 25(OH)D showed a significant positive correlation with EFG (R = 0.39, p < 0.05) and IL-15 (R = 0.39, p < 0.05), and a borderline significant association with IFNγ (R = 0.33, p = 0.06) in male patients with COVID-19." (PMID 36554094, 2022). "Therefore, higher levels of anti-SARS-CoV-2 antibodies, stimulated T-cell interferon-gamma production, or even both cannot be considered—unambiguously and definitely—as determinants of sufficient protection or being more susceptible to contracting COVID-19." (PMID 36146624, 2022). "Therefore, it is interesting that this pathway is preferentially associated with IFNG in COVID-19." (PMID 35217532, 2022). "Of note, IFNγ is an essential trigger of antimicrobial pulmonary responses, but increased IFNγ levels in COVID-19 blood and airways samples are associated with pathogenesis and pulmonary tissue damage, possibly through a detrimental effect of IFNγ on epithelial cells." (PMID 34957382, 2022). "However, a genetic difference that impairs interferon gamma (IFNγ) immune response resulting in unusually severe disease on encountering specific infections, such as the mycobacteria causing tuberculosis, has also recently been found relevant to COVID-19." (PMID 34911594, 2021). "IFNG was solely expressed in lymphocytes and especially elevated in the Post-COVID-19 and MIS-C groups." (PMID 39994453, 2025). "The effectiveness of the response of Th1 determines the severity of the disease, and patients with moderate and mild COVID-19 had a high frequency of IFNγ-producing Th1 cells." (PMID 41376646, 2025). "In severe COVID-19 cases (both SevereA and SevereD), NK cells exhibit significantly higher expression levels of IFNγ, while interferon-stimulated gene 15 (ISG15), and Myxovirus resistance protein 1 (MX1) were highly expressed in moderate cases." (PMID 39928675, 2025). "Studies indicate that pregnant women with COVID-19, particularly in their third trimester, experience a dysregulation of innate immunity, characterized by lower levels of IFNγ and reduced expression of CD14 and HLA-DR on monocytes." (PMID 40497938, 2025). "Severe COVID-19 is often followed by immune cell dysregulation, manifesting in the downsurge of IFNγ-producing Th cells (Th1 and Th17.1), Th17 and Treg levels, with the increase of Th2 levels in peripheral blood." (PMID 41376646, 2025). "In contrast, the expression levels of SOCS1 and IFNG remained stable throughout the hospital stay in patients with severe COVID-19." (PMID 40927375, 2025). "GSEA revealed upregulation of IFNγ-stimulated and IFNα-stimulated genes in vFB1.0 and vFB5 in Post-COVID-19." (PMID 39994453, 2025).
COVID-19 (continued). "Some studies have reported increased viral resistance in RhD-negative individuals, particularly against influenza A virus (potentially due to an amplified interferon-gamma signaling axis) and COVID-19." (PMID 41303137, 2025). "Severe cases of COVID-19 are often characterized by a cytokine storm, where excessive levels of proinflammatory cytokines, including IFNG, contribute to severe lung damage and multiorgan failure." (PMID 40919176, 2025). "Strikingly, in the Post-COVID-19 group, upregulated gene sets related to interferon-γ (IFNγ) signaling in multiple cell types." (PMID 39994453, 2025). "COVID-19 related genes were enriched for immune system, neutrophil degranulation and interferon gamma signalling as previously reported in other studies in adults." (PMID 41279033, 2025). "According to our results, it is reasonable to assume that the induction of EndMT in COVID-19 is also ascribable to the presence of several cytokines secreted by macrophages in CM_S1 medium, including IL-1β, IL-6, TNFα, and IFNγ." (PMID 40943589, 2025). "The correlation between decreased tryptophan, increased kynurenine levels and higher concentrations of proinflammatory cytokines such as IFNγ in COVID-19 patients has also been described in other studies." (PMID 39085233, 2024). "A study of IFNγ in almost 2000 outpatients presenting with COVID-19 within seven days of infection showed a halving of subsequent hospitalization compared to those receiving a placebo despite high vaccination rates." (PMID 39000027, 2024). "After the validation set (GSE171110) analysis, only four genes, namely IL-6R, TLR4, TLR2, and IFNG, showed expression changes similar to those of the training set in COVID-19." (PMID 38165854, 2024). "People with PCC showed low levels of Th1 cells, similar to individuals with severe and critical COVID-19, although these cells presented a higher capacity to express IFNγ in response to stimulation." (PMID 39257580, 2024). "To profile the initial SARS-CoV-2-specific cellular immune response in relation to COVID-19 severity and clinical outcome, we measured the number of virus-specific (IFNγ+) T cells in acute phase." (PMID 38811527, 2024). "The processes underlying of SARS-CoV-2-induced lung fibrosis are not completely understood, but imbalances of the renin–angiotensin system and low levels of circulating interferon gamma have been reported as potentially relevant to fibrosis following COVID-19." (PMID 38248798, 2024). "The lowest levels of IFNγ in early disease were observed in those who succumbed to their disease by COVID-19." (PMID 39519178, 2024). "It was previously shown in another mouse-adapted model of SARS-CoV-2 and in the transgenic K18-hACE2 mouse model of COVID-19 that genetic deficiency in TNF and simultaneous pharmacologic inhibition of TNF and IFNγ, respectively, attenuated disease severity." (PMID 38514848, 2024). "The contribution of type II IFN, IFNγ, to protection or pathology during COVID-19 is less well understood." (PMID 38950078, 2024). "Men with COVID-19 or other viral infections expressed more high-titer IFNα c-aAb and IFNγ c-aAb, respectively, compared to patients with bacterial infection." (PMID 39606243, 2024). "Individuals who succumbed to COVID-19 had the lowest levels of IFNγ in the early stages of the disease." (PMID 39519178, 2024). "In total, these studies suggest that the greatest impact of IFNγ on COVID-19 is in the earlier stages of infection." (PMID 39000027, 2024). "Among the pro-inflammatory cytokines observed in COVID-19 patients, interleukin-6 (IL-6), interleukin-1-beta (IL-1β), interferon-gamma (IFN-γ) and tumor necrosis factor-alpha (TNF-α) are generally associated with illness progression." (PMID 39199315, 2024). "A study has found that inflammatory factors including IL-2, YKL40, IL-4, IL-6, IL-10, sCD40L, TNF-α, IL-1Ra, interferon-gamma (IFN-γ), and CRP, are associated with cognitive impairment in COVID-19 patients." (PMID 38012459, 2024).
COVID-19 (continued). "Consistent with this, subjects who suffered from respiratory infections prior to contracting SARS-CoV-2 seem to have a more robust immune response (including an IFNγ response), resulting in milder COVID-19." (PMID 39000027, 2024). "Children with acute MIS-C tend to have elevated CD8+IFNγ values compared to the other study groups, especially compared to convalescent COVID-19 patients, indicating the involvement of IFNγ in the mechanisms of acute phase MIS-C." (PMID 39594853, 2024). "In particular, a study linking COVID-19 and CH showed an increased inflammatory response from monocytes in severe COVID-19 patients with CH, mediated via interferon gamma (IFN-γ) and TNF-α signaling signatures." (PMID 39641768, 2024). "T cell responses among COVID-19 survivors were evaluated using direct ex vivo interferon gamma (IFNγ) T cell ELISpot." (PMID 38322252, 2024). "Elevated IL-18 and IFNγ levels were found in COVID-19 patients recently and their levels are known to be correlated to various lung diseases including ALI and acute respiratory distress syndrome (ARDS)." (PMID 38983847, 2024). "Children with MIS-C after acute COVID-19 infection were identified with highly active T cells for IL-17 and IFNγ production compared to those with uncomplicated convalescent COVID-19." (PMID 39594853, 2024). "IFNγ and molecules induced by IFNγR signaling (e.g., CXCL10) have been associated with severe COVID-19 and the development of acute respiratory distress syndrome." (PMID 38950078, 2024). "NHP models that better recapitulate severe COVID-19 are needed to directly test the therapeutic potential of IFNγ blockade during SARS-CoV-2 infection." (PMID 38950078, 2024). "This study aimed to assess the efficacy of the SARS-CoV-2 vaccine in possibly immunocompromised children with rheumatic disease while utilizing the interferon-gamma release assay (IGRA) as a marker for COVID-19 immunity in the study follow-up." (PMID 38731052, 2024). "Here we examine the roles of the prototypic pro- and anti-inflammatory cytokines IFNγ and IL-10 using the rhesus macaque model of mild COVID-19." (PMID 38950078, 2024). "The remaining IL6R, IFNG, TLR4, and TLR2 genes (feature gene) were the most likely COVID-19 pathogenic genes that progressed into CRS." (PMID 38165854, 2024). "Administration of IFNγ to immunocompromised individuals with severe COVID-19 resulted in rapid declines in SARS-CoV-2 viral loads." (PMID 38950078, 2024). "Recent work has also highlighted likely role of IL-15 in monocytes, along with CD8 T cells, in COVID-19–recovered males leading to higher IFNG and increased in antibody responses after influenza vaccination." (PMID 39331702, 2024). "The distribution of c-aAb differed significantly across the pathogen groups for IFNα, IFNβ, and IFNγ c-aAb in the Surviving Pneumonia study cohort, with the distribution skewed higher for the COVID-19 group in relation to the bacterial pathogen group." (PMID 39606243, 2024). "On the other hand, it is also reported that the expression of IFNγ is significantly reduced in severe COVID-19 hospitalized patients." (PMID 38542436, 2024). "MISC_A had lower CD4+CD8+IFNγ+/million CD3+ median (IQR) values compared to COVID-19 (p-value: 0.02) and controls (p-value: 0.03)." (PMID 39594853, 2024). "Acute COVID-19 children had significantly elevated levels of cytokines, IFNγ, IL-2, TNFα, IL-1α, IL-1β and IFNα in comparison to convalescent children." (PMID 37013538, 2023). "Gene set enrichment analysis (GSEA) on each set of DEGs revealed high enrichment for interferon-alpha/beta (IFN-α/β) signaling and interferon-gamma (IFN-γ) signaling in both COVID-19 and HIV-1+ PBMCs." (PMID 36992700, 2023). "The aim of this study was to investigate the predictive utility of interleukin (IL)-6, IL-8, IL-10, IL-12, tumor necrosis factor alpha (TNF-α), and interferon gamma (IFN-γ) measurement in patients with COVID-19." (PMID 37969879, 2023).
COVID-19 (continued). "Another study conducted in unvaccinated patients further confirmed that SARS-CoV-2 specific T-cells were present also during asymptomatic SARS-CoV-2 infections, with a similar initial Interferon-Gamma (IFNγ) secreting T-cell count to severe COVID-19 patients." (PMID 36757971, 2023). "This pilot study investigated interferon gamma inducible biochemical pathways (namely Trp catabolism, neopterin, tyrosine [Tyr], and nitrite formation) during acute COVID-19 and reconvalescence." (PMID 37038445, 2023). "COVID-19’s upstream regulator, interferon-gamma (IFNG), is downregulated upon the infection of SARS-CoV-2, which leads to the downregulation of ACE2." (PMID 37686360, 2023). "We then employed IPA’s molecule activity predictor (MAP) tool to simulate the inhibition of IFNG to mimic COVID-19, which downregulated ACE2 expression." (PMID 37686360, 2023). "Functional enrichment analysis showed that upregulated DEGs in the 2V7 and 2V14 groups were enriched in the “response to virus”, “lymphocyte differentiation” and “response to interferon-gamma” pathways, which had previously been reported in COVID-19 patients." (PMID 36987861, 2023). "The reason behind the cytokine storm that increased the severity of COVID-19 is (a) hyperinflammatory response and (b) delayed interferon-gamma response in individuals with diabetes." (PMID 36839456, 2023). "More robust upregulation of mRNA expression for FoxP3, STAT5+, ROR alpha+, and IFNγ R1 was detected in severe COVID-19 patients compared to mild groups." (PMID 37569646, 2023). "Strikingly, other type 1 cytokines, such as IL-12, IFNγ and IL-7, were significantly lower in long-term carriers compared with regular COVID-19 patients at disease onset (<7 DSSO)." (PMID 37529320, 2023). "Inhibitors of janus kinase (JAK) block the intracellular signalling pathways of cytokines that promote and sustain inflammation in severe COVID-19, including IL-2, IL-6, IL-10, GM-CSF and IFNγ." (PMID 36941580, 2023). "In this study, we compared the vaccine response of individuals living with immunodeficiency with healthy controls in terms of interferon gamma (IFN-γ) production and spike protein-specific antibody level post primary COVID-19 vaccination and booster vaccines." (PMID 37033955, 2023). "The increase of IFNγ indicates a Th1-skewed response during COVID-19, and the increase in mRNA IFNγR1 transcription factor further supported this." (PMID 37569646, 2023). "CD4+ T cells from severe COVID-19 patients had decreased expression of IFNγ and IL-17A in relation to cells from patients with the moderate form of the disease or healthy donors." (PMID 37523305, 2023). "Apart from the predictive power of the IFNγ/IL-9 ratio, this study’s findings indicate that severe patients with COVID-19 expressed high levels of all tested cytokines." (PMID 37569646, 2023). "SARS-CoV-2-specific T cell responses were first measured with an interferon gamma (IFN-γ) ELISpot assay using PBMCs from 38 individuals who recovered from COVID-19." (PMID 37428088, 2023). "In humans, a single-cell transcriptional study performed in PBMCs from patients with COVID-19 suggested that the IFNα and IFNγ function in T cells and dendritic cells promote disease severity by activating STAT1." (PMID 37893073, 2023). "Convalescent COVID-19 children had elevated levels of IFNγ, IL-2, TNFα, IL-1α, IL-1β, IFNα, IFNβ, IL-6, IL-12, IL-17A, IL-10 and G-CSF in comparison to control children." (PMID 37013538, 2023). "The current study showed that patients under CHD hospitalized for moderate COVID-19 have increased circulating levels of TNFα, IFNγ and PDGF-A, decreased CD14-lymphocytes, decreased CD19-lymphocytes and decreased expression of HLA-DR on CD14-monocytes." (PMID 37674148, 2023). "At the same time, IFNG is the Th1 immune response against Leimaniasis; a case study also reported co-infection of Leimaniasis with COVID-19 in an immunocompromised patient." (PMID 36989283, 2023).
COVID-19 (continued). "Epitopes that included amino acid residues at 31–33, which are absent in the B.1.1.529 variant, exhibited low-intensity binding of Abs but stimulated IFNγ release in COVID-19 convalescents." (PMID 36680269, 2023). "Another study analyzing SARS-CoV-2-specific T cells in asymptomatic and symptomatic COVID-19 patients, showed that the levels of IFNγ, interleukins-2, 6, and TNF were higher in the asymptomatic cases than in the symptomatic patients." (PMID 37869674, 2023). "Recently, IFNγ therapy was followed by clinical improvement in five critically ill COVID-19 patients with bacterial complications." (PMID 36829233, 2023). "In support of the relationship between type II and III IFNs, we recorded a dysregulation in IFNγ and IFNλ gene expression levels in those patients with changed LDH, CRP and D-dimer values, which are known inflammatory markers associated with COVID-19 severity." (PMID 36985262, 2023). "Convalescent COVID-19 children had elevated levels of IFNγ, IL-2, TNFα, IL-1α, IL-1β, IFNα, IFNβ, IL-6, IL-12, IL-17A and G-CSF in comparison to control children." (PMID 37013538, 2023). "This is interesting in light of the low IFNγ found in COVID-19 patients in our study, particularly in the severe group, where six patients had secondary bacterial complications." (PMID 36829233, 2023). "Our findings are in agreement with previously reported data showing increased levels of inflammatory cytokines, such as IL-1β, TNF and IFNγ, and oxidative stress together with impaired spermatogenesis in men recovering from COVID-19." (PMID 37497433, 2023). "Relationships were drawn from COVID-19 to IFNG and IFNG to ACE2 and, then, to the overlapping molecules using IPA’s “Connect” and “Pathway Explorer” tools." (PMID 37686360, 2023). "Increased IL-6 and granzyme B were found to predict liver injury in COVID-19 patients, whereas interferon-gamma (IFN-γ), IL-1 receptor-a (IL-1Ra) and PD-L1 were predictors of remarkable radiological findings." (PMID 35529862, 2022). "IFNγ is a type I interferon and has been shown to be an important anti-viral response cytokine related to COVID-19 severity." (PMID 35079048, 2022). "A similar hyper induction of proinflammatory cytokines, such as IL6, IL1B, and IFNG, was observed in COVID-19 patients, and the level of induction in these cases was proportional to the severity of the disease." (PMID 35740365, 2022). "Highlighting the functional impairments, NK cells from people with COVID-19 co-cultured with virally-infected cells were less able to produce IFNγ and TNFα and reduce virus protein levels than th ose isolated from healthy individuals." (PMID 38566903, 2022). "Recently Dr. Shin’s group beautifully showed that PD-1 expressing CD8+ T cells in COVID-19 were functionally active in terms of IFNγ production." (PMID 36526616, 2022). "Therefore, the severity of COVID-19 may be caused by the down expression of the IFNG." (PMID 35422859, 2022). "As regards the cytokines panel, all but IFNγ and TNFα showed increased serum concentration in COVID-19 patients with more severe pneumonia." (PMID 35563218, 2022). "The levels of TNFa, IL-6, IL-1b, IFNg, IL-2, and IL-10 have been reported as inflammatory cytokines in COVID-19." (PMID 35669157, 2022). "Based on these two major pathobiological mechanisms involved in the pathogenesis of severe COVID-19, two novel markers have been recently proposed: MR-proADM and the in vitro measurement of IFNγ." (PMID 36016305, 2022). "Serological responses were measured by quantifying IgG levels against the spike-receptor-binding-domain of SARS-CoV-2, and cellular responses (in a subgroup analysis) by quantifying IFNγ secretion in blood incubated with COVID-19 spike-antigen." (PMID 35432335, 2022). "Our results show that surviving severe COVID-19 patients have lower circulating levels of IFNγ, IL-17A and sIL-4R than those with fatal outcomes." (PMID 36142255, 2022).